CCND2 (cyclin D2)
Diseases named in the same sentence as CCND2 in open-access papers (continued):
Sharing a sentence is not in itself a finding about the gene and the disease.
gastric cancer (continued). "Genomic alterations in CCND2 are reported in multiple malignances including renal cell carcinoma and colon cancer and CCND2 overexpression is related to poor overall survival in patients with gastric cancer." (PMID 35083150, 2021). "HOTAIR knockdown had antitumor effects by suppressing CCND1 and CCND2 expression by stimulating miRNA‐206 in gastric cancer in vitro study." (PMID 33473276, 2021). "Previously, we observed that the presence of Dkk3 overexpression and recombinant Dkk3 triggered G1 phase arrest in gastric cancer cells by downregulating Cyclin D2 and Cyclin E expression via the Wnt/β-catenin pathway." (PMID 33425757, 2020). "When stratified by tumor type, increased CCND2 expression correlated with lower OS in gastric cancer (HR = 2.20, 95% CI: 1.66‐2.92, P = 0.535)." (PMID 30950241, 2019). "RMRP suppressed the expression of miR-206 and regulated the cell cycle by modulating Cyclin D2 expression in gastric cancer cell." (PMID 27906963, 2016). "RMRP inhibited the expression of miR-206 and regulated the cell cycle through modulating Cyclin D2 expression in gastric cancer cell." (PMID 27906963, 2016). "Previous study showed that RMRP increased aggressive gastric cancer by regulating Cyclin D2 as the ceRNA for miR-206." (PMID 27906963, 2016). "As previously reported, overexpression of CCND2 has been noted in gastric cancer, as the results showed overexpression of CCND2 closely correlates with cancer progression and supposed to be an independent prognostic factor." (PMID 27583477, 2016). "The demethylation of melanoma antigen (MAGE), synuclein-gamma (SNCG) and cyclin D2 has been observed in gastric cancer." (PMID 25997695, 2015). "miR-206 has previously been shown to inhibit gastric cancer proliferation in part by suppressing cyclin D2." (PMID 26186594, 2015). "Previous studies showed that the ability of 5-Aza-dC to enhance expression of cyclin D2 was more marked if gastric cancer cells were treated for at least 5 days." (PMID 22303414, 2011). "Over-expression of cyclin D2 correlates with progression and poor prognosis in gastric cancer, colon cancer and granulosa cell tumors of the ovary." (PMID 22303414, 2011). "Overexpression of CCND2 was reported in ovarian granulose cell tumors, gastric cancer and colon cancer." (PMID 20418948, 2010). "The inverse correlation between BCL6 and cyclin D2 was also found in HB-EGF-positive human gastric cancers." (PMID 19337254, 2009). "In the present study, our immunohistochemical analysis revealed an inverse correlation between BCL6 and cyclin D2 expression in the group of HB-EGF-positive human gastric cancers." (PMID 19337254, 2009). "We found that BCL6 expression is closely linked with the downregulation of cyclin D2, as determined by immunohistochemistry, in cases of HB-EGF-positive human gastric cancer." (PMID 19337254, 2009). "In the present study, we investigated the interaction of BCL6 with HB-EGF-CTF and the mechanism of cyclin D2 expression by this interaction in gastric cancer cell lines, which express endogenous HB-EGF, BCL6, and cyclin D2." (PMID 19337254, 2009). "Considering these facts, our data indicate that HB-EGF-CTF nuclear translocation caused the degradation of BCL6 and that this degradation reverses cyclin D2 repression in gastric cancer cell lines that express endogenous BCL6, HB-EGF-CTF, and cyclin D2." (PMID 19337254, 2009). "For example, overexpression of cyclin D2 in gastric cancer was shown to correlate with disease progression and poor prognosis." (PMID 16012517, 2005). "In summary, transcriptional silencing by promoter hypermethylation of the cyclin D2 gene is detected in a subset of gastric cancer." (PMID 12771922, 2003). "We first examined the promoter methylation status and expression of cyclin D2 in gastric cancer cell lines." (PMID 12771922, 2003). "We next examined the potential association between clinicopathological and molecular characteristics of gastric cancer with cyclin D2 methylation." (PMID 12771922, 2003).
gastric cancer (continued). "Overexpression of cyclin D2 has been reported in gastric cancer and is shown to correlate with disease progression and poor prognosis." (PMID 12771922, 2003). "The aim of the current study was to examine the methylation status of the CpG sites in the cyclin D2 promoter region of gastric cancer by methylation-specific PCR (MSP) and bisulphite DNA sequencing." (PMID 12771922, 2003). "Bisulphite sequencing was also performed in seven randomly selected gastric cancers: two with cyclin D2 expression (T2, T39), two with low cyclin D2 expression (T8, T35) and three cyclin D2-negative (T4, T6, T30) cancers." (PMID 12771922, 2003). "We also correlated the expression of cyclin D2 with cyclin D2 promoter hypermethylation in gastric cancer." (PMID 12771922, 2003). "We investigated the role of promoter hypermethylation in the transcriptional silencing of cyclin D2 in five gastric cell lines and 47 primary gastric carcinomas." (PMID 12771922, 2003). "In gastric cancer, some studies suggest that high methylation of CCND2 may promote cellular proliferation." (PMID 40678058, 2025). "The relationship between miR-154-5p and CCND2 in gastric cancer was further elucidated." (PMID 40708910, 2025). "Although typically associated with hematologic malignancies, activating/sensitizing CCND2 gene alterations reportedly occur in up to 23% of testicular cancers and may occur infrequently in some cases of human gastric carcinoma." (PMID 40723239, 2025). "Thus, our research revealed that miR-98-5p can suppress gastric cancer development by targeting CCND2." (PMID 35266852, 2022). "Similarly, CCND2 level was enhanced in gastric cancer cell lines (AGS, SNU-5, and NCI-N87) compared with that in the GES-1 normal gastric epithelial cells." (PMID 35266852, 2022). "In this study, we hypothesized that TTTY15 plays a role in gastric cancer by regulating miR-98-5p/CCND2." (PMID 35266852, 2022). "Thus, the lncRNA TTTY15/miR-98-5p/CCND2 axis is a potential therapeutic target for gastric cancer, and our results provide new insights for clinical treatment approaches." (PMID 35266852, 2022). "Consistent with previous research, our study found that miR-98-5p could promote gastric cancer cell apoptosis in addition to reducing cell proliferation, which could be partly offset by overexpression of CCND2." (PMID 35266852, 2022). "In conclusion, HOTAIR’s positive regulation of CCND1 and CCND2 in gastric cancer may be realized by reverse regulation of miRNA‐206." (PMID 33473276, 2021). "Our research supports that targeting HOTAIR‐miRNA‐206‐CCND1/CCND2 signal pathway can be accepted as a potential method for treatment of gastric cancer, providing a new basis for further understanding of the occurrence and development mechanism of gastric cancer." (PMID 33473276, 2021). "In summary, this meta‐analysis suggested that CCND2 played an oncogenic role in gastric cancer, whereas it could also be a tumor suppressor in NSCLC." (PMID 30950241, 2019). "CCND2 was generally considered as a protooncogene in various tumors, overexpression of CCND2 has been reported in testicular germ cell tumor cell lines, colon cancer and gastric cancer correlating with tumor progression and poor prognosis." (PMID 27583477, 2016). "Based on previous reports, cyclin D2 is elevated in gastric cancer when miR-206 is affected." (PMID 26186594, 2015). "The hypomethylation of the cyclin D2 promoter is observed in 71% of cases of gastric cancer." (PMID 25997695, 2015). "Our data indicate that BCL6 interacts with HB-EGF-CTF and that this interaction might induce the cyclin D2 expression in human gastric cancer." (PMID 19337254, 2009). "This interaction causes nuclear export and degradation of BCL6 and might result in the downregulation of BCL6 repressor activity for the cyclin D2 promoter in gastric cancer cells." (PMID 19337254, 2009).
gastric cancer (continued). "Thus, we found that BCL6 expression correlated with the downregulation of cyclin D2 expression in human gastric cancer tissues that are HB-EGF positive." (PMID 19337254, 2009). "The mechanism that BCL6 regulate transcription of cyclin D2 might also happen in gastric cancer cells." (PMID 19337254, 2009). "We performed immunohistochemical analyses of BCL6, HB-EGF and cyclin D2 in human gastric cancers." (PMID 19337254, 2009). "Among the 47 primary gastric cancers, cyclin D2 hypermethylation was detected in 23 (48.9%) cases." (PMID 12771922, 2003). "This implies that CCND2 may be an oncogene involved in gastric cancer." (PMID 35266852, 2022). "Our study showed that cyclin D2 hypermethylation is associated with loss of cyclin D2 expression in a subset of gastric cancers, which may suggest an alternative gastric carcinogenesis pathway in the absence of cyclin D2 expression." (PMID 12771922, 2003). "Meanwhile, stable transfection of two shRNAs targeting the junction of circ-HuR resulted in its down-regulation and up-regulation of HuR and its downstream genes (CCND2 and CTNNB1) in gastric cancer cells." (PMID 31718709, 2019). "We also immunohistochemically studied 100 surgical specimens of advanced gastric cancers to analyse the expression of HB-EGF, BCL6, and cyclin D2." (PMID 19337254, 2009). "In the HB-EGF-positive group of human gastric cancer samples, BCL6 expression is also inversely correlated with cyclin D2 expression." (PMID 19337254, 2009). "Cytoplasmic translocated BCL6 was degraded by the ubiquitin/proteasome pathway, and the degradation of BCL6 induced cyclin D2 expression in gastric cancer cell lines that expressed endogenous BCL6, HB-EGF-CTF, and cyclin D2." (PMID 19337254, 2009). "Gli-1 is known to induce expression of proliferative genes such as cyclin D2, FOXM1 and the ras-ERK pathway and to reduce expression of cell cycle repressor p21/CIP1 in gastric carcinoma cell lines." (PMID 17505514, 2007). "Collectively, our study further clarified that the antitumor effect of HOTAIR silencing in gastric cancer might resulted from the involvement of CCND1 and CCND2 medicated by miRNA‐206." (PMID 33473276, 2021). "Interestingly, after miRNA‐206 inhibitor's transfection into gastric cancer cells, along with the recovery of the biological activity of SGC‐7901, CCND1 and CCND2 protein expression were enhanced simultaneously." (PMID 33473276, 2021). "In this research, HOTAIR silencing was effective in inhibiting the expression of CCND1 and CCND2 in gastric cancer cells, which might be related to HOTAIR silence's suppression of the biological activity of gastric cancer." (PMID 33473276, 2021). "We found that CCND2 was significantly promoter hypermethylated and lower when expressed in lung adenocarcinoma and TNBC as compared with adjacent normal tissues and other cancers, such as colon cancer, liver cancer, gastric cancer, and esophageal cancer." (PMID 30308939, 2018). "Furthermore, they demonstrated that miR-29 family directly targeted CCND2 and MMP2 to influence gastric cancer progression." (PMID 28173777, 2017). "We and others have demonstrated that cyclin D2 mRNA and/or protein are absent in 30–70% of gastric cancers." (PMID 12771922, 2003). "In this study, methylation of cyclin D2 promoter region appears to be a tumour-specific event since methylation was detected only in gastric cancer and cancer cell lines, but not in normal gastric mucosa." (PMID 12771922, 2003). "Our results suggest that the development of a subset of gastric cancer is independent of cyclin D2 expression." (PMID 12771922, 2003). "The absence of CCND2 expression by promoter methylation is also observed in gastric cancer." (PMID 27583477, 2016). "However, there is no available information on the methylation status of the cyclin D2 gene in gastric cancer." (PMID 12771922, 2003). "On the other hand, cyclin D2 expression is not universal in gastric cancer." (PMID 12771922, 2003).
gastric cancer (continued). "Expression of cyclin D2 is absent in 30–70% of gastric cancers." (PMID 12771922, 2003). "Moreover, it offers an explanation for the lack of cyclin D2 expression in a subset of gastric cancer." (PMID 12771922, 2003). "Intuitively, cyclin D2 expression may not be necessary in the development of a subset of gastric cancer." (PMID 12771922, 2003). "Additionally, we showed that most human gastric cancers (15 out of 23, 65.2%) with cyclin D2 promoter hypermethylation had no cyclin D2 mRNA expression whereas the majority (21 out of 24, 87.5%) of tumours with unmethylated cyclin D2 promoter region had cyclin D2 expression." (PMID 12771922, 2003). "Three gastric cancer cell lines (KATOIII, AGS and NCI-N87) with dense methylation at the CpG islands do not express cyclin D2 mRNA and protein." (PMID 12771922, 2003).
lung cancer (33 papers, 2010 to 2025). A malignant neoplasm involving the lung. "Clinical data have suggested that CCND2 was down-regulated in lung cancer and it was associated with lymph node metastasis, distant metastasis, and a poor prognosis (p = 0.014, and p = 0.017, respectively)." (PMID 30308939, 2018). "Combined, these results reveal a progression in the rate of CCND2 hypermethylation in the lung, corresponding with the risk for developing lung cancer." (PMID 21577262, 2011). "However, a study looking at non–small cell lung cancer showed reduced expression of CCND2, and the level of CCND2 was adversely associated with recurrence-free survival in patients with non–small cell lung cancer." (PMID 37204480, 2023). "Additionally, CCND2 hypermethylation was associated with a poor prognosis in breast and lung cancer patients." (PMID 30308939, 2018). "Notably, hypermethylation of CCND2 was associated with female lung cancer and lung adenocarcinoma (p < 0.001)." (PMID 30308939, 2018). "In conclusion, CCND2 is a good diagnostic marker and drug target for breast and lung cancer." (PMID 30308939, 2018). "In this study, miR-4317 targets fibroblast growth factor 9 (FGF9) and cyclin D2 (CCND2), affecting the migration and invasion of lung cancer cells." (PMID 39408656, 2024). "By binding to these microRNAs, RP11-805J14.5 effectively reduces their availability for binding to CCND2 mRNA, thereby increasing the expression of CCND2 and potentially promoting cell cycle progression in lung cancer cells." (PMID 37835417, 2023). "While the accumulation of CCND2 is the most common disease mechanism associated with CCND2-associated disorders, a number of cancers have been found to have reduced CCND2 due to CCND2 hypermethylation, particularly breast and lung cancers." (PMID 37510349, 2023). "The results indicated that CCND2 was expressed in normal lung cells, but it was underexpressed in lung cancer cells." (PMID 30308939, 2018). "CCND2 inhibits lung cancer migration and it was found to be a good prognostic factor; thus, it can serve as an ideal drug target." (PMID 30308939, 2018). "Ectopic expression of miR-329 in lung cancer cell lines substantially repressed cell growth as evidenced by cell viability assay, colony formation assay and BrdU staining, through inhibiting cyclin D1, cyclin D2 and up-regulatiing p57(Kip2) and p21(WAF1/CIP1)." (PMID 26909600, 2016). "In addition, miR-326 also inhibited cyclin D1, cyclin D2 and promoted p57 and p21 expression levels in lung cancer cells, which further contributed to the growth-delay efficacy of miR-326." (PMID 26840018, 2016). "In addition, miR-134 also inhibited cyclin D1, cyclin D2 and promoted p57 and p21 expression levels in lung cancer cells, which further contributed to the growth-delay efficacy of miR-134." (PMID 27166267, 2016). "In addition, miR-206 also inhibited CCND1 and CCND2 and increased p57 expression levels in lung cancer cells, which further contributed to the growth-delay efficacy of miR-206." (PMID 26325180, 2015). "Importantly, we observed that CCND2, which is known to be frequently hypermethylated in lung cancer tissue, was hypermethylated more frequently in ever-smokers (26%) than in never-smokers (3%)." (PMID 21577262, 2011). "Therefore, for future personalized medicine, a CCND2 inducer drug might be suitable for TNBC or female lung cancer and lung adenocarcinoma patients with low CCND2 expression, but not for patients with CCND2 mutation or amplification." (PMID 30308939, 2018). "It was shown that C. gigantea inhibits the growth of human lung cancer cells by downregulating the genes Akt, CDK4, CCND1, and CCND2, which are important for cell cycle arrest in the G1/S phase." (PMID 40142097, 2025). "RUNX1 stimulated G1 to S progression in hematopoietic cells, partly via transcriptional induction of cyclin D2 promoter, whereas RUNX1 depletion resulted in an increased E2F1 mRNA levels in lung cancer cells." (PMID 32498288, 2020).
lung cancer (continued). "In this study, transcriptome profiling and RT-qPCR validation revealed that PGL arrests the cell cycle via downregulation of the expression of RB1, CCNH, MDM2, ACCN4, CCND2, GADD45A, and GADD45B in lung cancer cells." (PMID 27355352, 2016). "Genes frequently methylated in lung cancer cell lines including SCGB3A1, ID4, CCND2 were found among the most commonly methylated in the lung tumors analyzed." (PMID 20849603, 2010). "MiR‐646 is downregulated in non‐small cell lung cancer (NSCLC) and could suppress the proliferation and EMT‐induced metastasis of NSCLC by suppressing FGF2 and CCND2." (PMID 32347652, 2020). "It is noteworthy that antroquinonol D still induced CCND2 expression in lung cancer cell lines without aberrant CCND2 promoter hypermethylation." (PMID 30308939, 2018). "In particular, SUSD2, CCND2, BCL2A1, and TMEM158 could be potential targets of JFK in human lung cancers." (PMID 27087825, 2016). "Second, miR-206 can directly regulate mRNA expression by targeting the 3′-UTR of MET and BCL2, and inhibit protein expression of cyclin D1 and gene expression of cyclin D1, cyclin D2 and matrix metalloproteinase 9 (MMP-9), while increased p57 gene expression in lung cancer cell (A549)." (PMID 26325180, 2015). "Cyclins are often upregulated in cancers; however, cyclin D1 has not been shown to be a negative prognostic factor in cancer, cyclin D2 is often methylated and thus downregulated in lung cancer, and cyclin D3 was suggested not to have a profound role in tumorigenesis." (PMID 25325012, 2014). "Also, as predicted, in ever-smokers, CCND2 was hypermethylated more frequently in samples from the upper lobes, which are known to suffer far more negative effects from cigarette smoke, such as lung cancer and emphysema." (PMID 21577262, 2011).